FGF21 (fibroblast growth factor 21)
Diseases named in the same sentence as FGF21 in open-access papers (continued):
Sharing a sentence is not in itself a finding about the gene and the disease.
Sepsis (continued). "This nano-construct, denoted as KMZ@FGF21, was loaded with the antioxidant/anti-inflammatory hormone, fibroblast growth factor 21 (FGF21), against sepsis-induced acute kidney injury (AKI)." (PMID 38637839, 2024). "Thus, FGF21 may be a potential biomarker for sepsis patients’ survival prediction." (PMID 36440004, 2022). "As for patients with sepsis and ARDS, the expression of FGF21 levels persistently increased until the peak time points of shock and death." (PMID 36440004, 2022). "This motivated our interest in the relationship between the dynamics changes of FGF21 and the prognosis of ARDS during sepsis in the present research." (PMID 34154595, 2021). "The present study, which compared patients with sepsis alone vs. sepsis and ARDS, identified much higher levels of serum FGF21 and pro-inflammatory factors (PCT, CRP, IL-6, and TNFα) in the Sepsis + ARDS group." (PMID 34154595, 2021). "Patients with inflammatory reactions, such as sepsis, pancreatitis, and systemic inflammatory response syndrome (SIRS), have increased serum levels of FGF21." (PMID 34154595, 2021). "Serum FGF21 levels are significantly increased in patients with sepsis and SIRS, suggesting a role for FGF21 in inflammation." (PMID 26483756, 2015). "Also, our study did not address the causal relationship between FGF21 and sepsis." (PMID 23999826, 2013). "Newer roles of FGF21 are emerging in critical diseases including acute lung injury/acute respiratory distress syndrome (ALI/ARDS), acute myocardial injury (AMI), acute kidney injury (AKI), sepsis, and liver failure." (PMID 39838305, 2025). "Unfortunately, population-related clinical trials with FGF21 or the analogs of FGF21 in the treatment of sepsis have not proceeded." (PMID 36440004, 2022). "Compared with patients who survive, FGF21 levels were nearly four times higher in patients with sepsis and ARDS who did not survive." (PMID 36440004, 2022). "In this study, we found that FGF21 is a promising prognostic biomarker for differentiating non-survivors and survivors among patients with Sepsis + ARDS." (PMID 34154595, 2021). "Non-survivors in the Sepsis + ARDS group had an almost fourfold greater level of FGF21 than survivors in this group (P < 0.05)." (PMID 34154595, 2021). "FGF21 was found to be significantly higher in patients with sepsis compared with those with noninfectious SIRS." (PMID 23999826, 2013). "Furthermore we found, in one patient with sepsis who presented with a second infection during the stay in ICU, an initial decrease followed by an increase in FGF21 levels paralleling the nosocomial infectious episode." (PMID 23999826, 2013). "In this study, we show for the first time that patients with sepsis have a significant elevation of FGF21 plasma levels, higher than patients with noninfectious SIRS or healthy subjects." (PMID 23999826, 2013). "FGF21 levels were higher in infectious than noninfectious sepsis." (PMID 39838305, 2025). "Endogenous FGF21 is not required for surviving critical illness induced by surgery and polymicrobial sepsis in mice but may exert some mild adaptive, muscle-protective effects, with attenuation of muscle weakness and lowering of cellular stress in muscle." (PMID 37537627, 2023). "Endogenous FGF21 is not required for sepsis survival, but may partially protect muscle force and may reduce cellular stress in muscle." (PMID 37537627, 2023). "We focus on the emerging roles of FGF21 and its potential effects in critical diseases including acute lung injury/acute respiratory distress syndrome (ALI/ARDS), acute myocardial injury (AMI), acute kidney injury (AKI), sepsis, and liver failure in this review." (PMID 36440004, 2022). "Hence, we aim to review and summarize the current status of FGF21 research in critical illness, including acute lung injury (ALI), acute respiratory distress syndrome (ARDS), acute myocardial injury (AMI), acute kidney injury (AKI), sepsis, and liver failure." (PMID 36440004, 2022).
Sepsis (continued). "Due to this, it should not come as a surprise that FGF21 levels in the circulation were elevated in both sepsis mouse models and patients with sepsis, indicating that this increase may act as a protective mechanism." (PMID 36440004, 2022). "The Sepsis + ARDS group had a greater respiratory rate, a lower PaO2/FiO2, a greater SOFA score, and higher levels of lactate (LAC), procalcitonin (PCT), C-reactive protein (CRP), interleukin 6 (IL-6), tumor necrosis factor α (TNFα), IL-10, and FGF21 (all P < 0.05)." (PMID 34154595, 2021). "Furthermore, non-survivors in the Sepsis + ARDS group had persistently increasing levels of FGF21 during their ICU stays, but survivors in the Sepsis + ARDS group had persistently declining levels." (PMID 34154595, 2021). "Thus, it is not surprising that the serum level of FGF21 was greater in patients with sepsis and ARDS." (PMID 34154595, 2021). "Thus, FGF21 is a promising biomarker for differentiating non-survivors and survivors among patients with Sepsis + ARDS." (PMID 34154595, 2021). "Also, FGF21 levels were significantly higher in patients with sepsis than in those with noninfectious SIRS." (PMID 23999826, 2013). "FGF21 is not a specific biomarker of sepsis because it is also increased in patients with SIRS." (PMID 23999826, 2013). "We examined the predictive values of FGF21 and SOFA at baseline for differentiating non-survivor and survivor patients with Sepsis + ARDS by use of receiver operating characteristic (ROC) curve analysis." (PMID 34154595, 2021). "Our analysis of disease progression in patients with sepsis and ARDS indicated the non-survivors had continuously increased serum levels of FGF21, and this was accompanied by persistent increases in the levels of multiple pro-inflammatory cytokines." (PMID 34154595, 2021). "Similarly, in patients with Sepsis and ARDS, non-survivors had a FGF21 value four times greater than in the survivors." (PMID 39838305, 2025). "FGF21 plasma levels measured at study entry correlated positively with the APACHE II score, but not with procalcitonin levels, nor with C-reactive protein, classical markers of sepsis." (PMID 23999826, 2013).
Cognitive impairment (18 papers, 2018 to 2025). Abnormal cognition is characterized by deficits in thinking, reasoning, or remembering. "In ME + FM patients, low circulating FGF-21 levels were also associated with worse cognitive outcomes, a finding consistent with reports of heightened symptom burden and cognitive deficits in comorbid ME + FM populations." (PMID 40868993, 2025). "Our results revealed that decreasing FGF19 and FGF21 levels were associated with cognitive impairment in MDD patients, which need further verification." (PMID 37266540, 2023). "This is in line with elevated circulating FGF21 and its expression in the brain, as well as alleviated synaptic loss and cognitive deficits." (PMID 36296980, 2022). "Any association between FGF21 level and cognitive impairment in thalassemic patients’ needs to be investigated further in a larger population." (PMID 33850218, 2021). "The possible role of FGF21 as a risk factor of cognitive impairment should be further explored in a prospective study." (PMID 29581470, 2018). "Increased plasma FGF21 levels in thalassemic patients is associated with cognitive impairment." (PMID 33850218, 2021). "Recombinant human FGF-21 could reduce the concentrations of total cholesterol, low-density lipoprotein, and high-density lipoprotein, inhibit neuroinflammation, and correct cognitive decline in cognitive impairment caused by hyperlipidaemia." (PMID 37214403, 2023). "The neuroprotective properties of FGF21 have also been explored in models of cognitive impairment induced by metabolic stress, such as high-fat diets [812, 1003, 1004]." (PMID 40407975, 2025). "Preclinical studies have demonstrated that systemic FGF21 administration exerts neuroprotective effects in rodent models of CNS injury and cognitive impairment." (PMID 40407975, 2025). "In turn, during some harmful events related to the nervous system, such as TBI, I/R injury, cognitive impairment and neurodegenerative diseases, FGF21 can also exert certain protective effects." (PMID 38049769, 2023). "More importantly, results from the Y-maze and Morris water maze, which are widely used to evaluate cognitive function and spatial memory, showed that FGF21 also markedly prevented the MPTP-induced cognitive impairment in mice with PD." (PMID 35002679, 2021). "The results showed that FGF21 significantly alleviated motor and cognitive impairment in mice with PD." (PMID 35002679, 2021). "This suggests that there is a greater positive correlation between FGF21 and the severity of cognitive impairment in those patients than any other metabolic parameters on the severity of cognitive impairment in those patients." (PMID 29581470, 2018). "Consequently, to develop therapies targeting FGF21 production induced by GLN for cognitive disorders, enhancing GLN’s bioavailability through dosage optimization and alternative administration methods is imperative to maximize its effects." (PMID 38673797, 2024). "In addition, a notable finding of this study is that FGF21 is also able to ameliorate cognitive impairment in PD as demonstrated by the Y maze test." (PMID 37334756, 2023). "FGF21 also showed brain-protective effects, with attenuation of LPS- or traumatic brain injury-induced behavior deficits and of ischemia-induced cerebral injury, motor disability, cognitive defects and ER stress." (PMID 37537627, 2023). "Similarly, FGF21 treatment improved metabolic dysfunction-related cognitive impairment and AD-like degeneration in obese rats." (PMID 36296980, 2022). "This study demonstrated that FGF21 level was independently associated with cognitive impairment in non-elderly patients but not in elderly patients." (PMID 29581470, 2018). "The results showed that FGF21 exerted numerous protective effects, including alleviation in Aβ25-35-induced neuronal apoptosis, tau pathology, mitochondrial damage, and oxidative stress, paralleled by a significant improvement in the animals’ cognitive deficits." (PMID 36296980, 2022).
Cognitive impairment (continued). "Our findings may suggest that FGF21 may play a potential role in attenuating cognitive impairment." (PMID 32267096, 2020). "Therapeutic strategies for individuals with low circulating FGF-21 and accompanying cognitive impairment or PEM should focus on enhancing mitochondrial resilience and amplifying FGF-21 signaling." (PMID 40868993, 2025). "Furthermore, the role of FGF21 resistance in the thalassemic patient should be explored in future research whether it is the pathogenesis of cognitive impairment or the adaptive process to prevent the effects of the high level of plasma FGF21 in thalassemic patients with cognitive impairment." (PMID 33850218, 2021). "The possible role of FGF21 level in cognitive impairment in non-elderly should be confirmed in a prospective study." (PMID 29581470, 2018). "Revealing a clear picture of how GLN-induced FGF21 production enhances learning and memory functions may illuminate a potential nondrug treatment for cognitive impairment." (PMID 38673797, 2024). "Thus, our results showed that FGF21 can not only improve motor function but also improve the non‐motor function, such as cognitive impairment." (PMID 37334756, 2023). "In addition, FGF21-associated upregulation of PGC-1α expression was reported to play an important role in metabolic remodeling, but no studies have evaluated the influence of this pathway on cognitive impairment so far." (PMID 37266540, 2023). "In the final probe test, FGF21 administration increased the residence time in the target quadrant and the number of crossing the original location of the platform in the APP/PS1 model, suggesting that FGF21 could alleviate cognitive impairment by directly acting on the central nervous system." (PMID 32724479, 2020). "There were no group differences in FGF-21, phosphatidylethanol, or bone markers; life quality measurements, i.e., 36-Item Short Form Health Survey (SF-36) and Symptom Checklist-92 (SCL-92); or cognition i.e., Screen for Cognitive Impairment in Psychiatry test (SCIP)." (PMID 36066977, 2022).
gestational diabetes (18 papers, 2011 to 2026). Carbohydrate intolerance first diagnosed during pregnancy. "Associations of serum FGF21 concentrations (pg/ml) early in the second trimester of pregnancy with the risk of gestational diabetes mellitus." (PMID 33995273, 2021). "As an important endocrine hormone regulating glucose metabolism, fibroblast growth factor 21 (FGF21) is increased in individuals with gestational diabetes mellitus (GDM) after 24 gestational weeks." (PMID 33995273, 2021). "Since reduced FGF19 level is a contributing factor in the development of gestational diabetes, it created much interest in understanding the role of FGF21." (PMID 30927227, 2019). "In the placentae of women with an uncomplicated pregnancy or gestational diabetes mellitus, there was a positive correlation between the gene expression levels of PPARα and FGF21 and a tendency for a positive correlation between PPARγ and FGF21." (PMID 25890271, 2015). "In the current study, we investigated serum FGF19 and FGF21 levels in patients with gestational diabetes mellitus (GDM) and explored their relationships with anthropometric and endocrine parameters." (PMID 24260557, 2013). "Although studies suggest that reduced FGF19 level may play a role in the pathophysiology of gestational diabetes, the increased FGF21 level may be a response to the disease." (PMID 30927227, 2019). "Placental FGF21 mRNA and protein expression is highly variable in normal pregnancies as well as in pregnancies affected by late-onset preeclampsia (current study) or gestational diabetes mellitus." (PMID 25890271, 2015). "The connection between fibroblast growth factor 21 (FGF21) and the likelihood of gestational diabetes mellitus (GDM) or preeclampsia (PE) has received more attention recently." (PMID 39819596, 2025). "In comparison to control subjects, plasma FGF21 levels were significantly higher in women with gestational diabetes mellitus (GDM)." (PMID 25592553, 2015). "We sought to study human cerebrospinal fluid (CSF) and corresponding circulating FGF21 levels in women with gestational diabetes mellitus (GDM) and in age and BMI matched control subjects." (PMID 23755203, 2013). "It has been reported that two endocrine FGFs (i.e. FGF21 and FGF19) can potentially regulate metabolic disorder in gestational diabetes." (PMID 35317005, 2022). "To evaluate the role of FGF21 in gestational diabetes mellitus (GDM), we collected visceral fat samples from three groups: non-pregnant chow diet female mice (ND-Virgin), pregnant chow diet female mice (ND-E18.5), and pregnant high-fat high-sucrose diet female mice (GDM-E18.5)." (PMID 39599611, 2024). "In contrast to our previous results in placentae from women with or without gestational diabetes, PPARα expression is not correlated to FGF21 expression." (PMID 25890271, 2015).
renal failure (18 papers, 2010 to 2025). "Currently, renal elimination is the main pathway for maintaining FGF21 serum levels, and the finding that FGF21 serum concentrations are elevated in patients with renal failure validates this conclusion." (PMID 36293317, 2022). "For instance, FGF21 treatment alleviated LPS-induced acute lung injury and protected against acetaminophen- or D-galactose-induced acute liver injury and cisplatin-induced acute kidney injury." (PMID 37537627, 2023). "In MMA, the renal complications and the high plasma FGF-21 levels could point toward a role of mitochondrial dysfunction in renal failure, which was also proposed by others." (PMID 30159853, 2018). "In summary, our results demonstrate that FGF21 ameliorates cisplatin-induced nephrotoxicity through SIRT1, preventing kidney failure and tubular cell damage." (PMID 32210821, 2020). "Furthermore, plasma FGF-21 levels were already elevated before the occurrence of kidney failure, nor was there an increase in plasma FGF-21 levels when renal function deteriorated." (PMID 30159853, 2018).